GJA3 (gap junction protein alpha 3)
Description:
Structural component of lens fiber gap junctions. Gap junctions are dodecameric channels that connect the cytoplasm of adjoining cells (By similarity). They are formed by the docking of two hexameric hemichannels, one from each cell membrane. Small molecules and ions diffuse from one cell to a neighboring cell via the central pore.
Synonyms: Cx46; CTRCT14; CZP3
Tractability: Antibody: UniProt places it where antibodies can reach, with high confidence; its Gene Ontology location is reachable by antibodies, with high confidence; UniProt predicts a signal peptide or a membrane-spanning region. PROTAC: ubiquitination databases record sites on it.
Gene: Protein-coding gene on chromosome 13 (20,138,252 to 20,161,615, reverse strand). Ensembl gene ENSG00000121743.
Subcellular location: Cell membrane; Cell junction, gap junction
Pathways (Reactome):
Vesicle-mediated transport: Gap junction assembly
Gene Ontology:
Molecular function: gap junction hemi-channel activity; gap junction channel activity
Biological process: gap junction-mediated intercellular transport; cell-cell signaling; cell communication; transmembrane transport; visual perception
Cellular component: connexin complex; plasma membrane; gap junction
Genetic constraint (gnomAD): Loss-of-function variants: 1 observed, 0.6 expected, observed/expected ratio (o/e) 1.67, 90% interval 0.33 to 1.92. That is too few expected variants to judge how well the gene tolerates losing a copy. Missense variants: 571 observed, 569.78 expected, observed/expected ratio (o/e) 1, 90% interval 0.94 to 1.07. Synonymous variants: 297 observed, 263.4 expected, observed/expected ratio (o/e) 1.13, 90% interval 1.02 to 1.24.
Homologues: Orthologues: chimpanzee GJA3 (99% identical), macaque GJA3 (90% identical), dog GJA3 (73% identical), mouse Gja3 (72% identical), rat Gja3 (71% identical), rabbit GJA3 (62% identical), zebrafish gja3 (59% identical), pig GJA3 (59% identical), tropical clawed frog gja3 (59% identical). Paralogues in human: GJA8 (41% identical), GJA1 (39% identical), GJA5 (38% identical), GJA4 (35% identical), GJA10 (33% identical), GJA9 (32% identical), GJC2 (29% identical), GJC1 (29% identical), GJB1 (26% identical), GJB2 (25% identical), GJB6 (25% identical), GJD2 (24% identical), and 8 more.
Diseases named in the same sentence as GJA3 in open-access papers:
GJA3 is named in the same sentence as 47 diseases in open-access papers, as found by Europe PMC text mining. Sharing a sentence is not in itself a finding about the gene and the disease. The quoted sentences say what the papers report.
cataract (59 papers, 2007 to 2026). Partial or complete opacity of the crystalline lens of one or both eyes that decreases visual acuity and eventually results in blindness. "In this study, we investigated genetic variants in CRYAA, CRYAB, CRYGC, CRYGD, CRYBA1, GJA8, and GJA3 genes in 94 patients with congenital isolated cataracts from 45 unrelated families." (PMID 37367076, 2023). "Dominantly inherited variants in GJA3 are known to cause numerous types of cataracts in various populations." (PMID 35008666, 2021). "Several strains of mice or rats that develop cataracts also harbor mutations of the GJA3 (Cx46) or GJA8 (Cx50) genes." (PMID 25517998, 2014). "The present study identified a novel mutation (c.559C>T) in the GJA3 gene associated with autosomal dominant pulverulent cataracts in a Chinese family." (PMID 21647269, 2011). "The mutation (P187L) in GJA3 described a Caucasian family with congenital cataracts, presenting with zonular pulverulent cataracts phenotype." (PMID 21647269, 2011). "In conclusion, we identified a novel mutation (P187S) in GJA3 associated with autosomal dominant nuclear pulverulent cataracts in a Chinese family." (PMID 21647269, 2011). "In this study, we detected a novel mutation (P187S) in GJA3 associated with autosomal dominant nuclear pulverulent cataracts in a Chinese family." (PMID 21647269, 2011). "Here, we report a heterozygous 130G>A transition in the connexin 46 gene (GJA3) associated with congenital nuclear cataract in a Chinese family, while it co-segregated completely with the disease phenotype." (PMID 20431721, 2010). "We identified three mutations being most likely causative for congenital or childhood cataracts in these families from India – one affects the GJA3 gene encoding connexin 46, the other two affect CRYBB2 encoding β-crystallin." (PMID 21031021, 2010). "The cataract phenotypes that are reported to be linked with the GJA3 mutations share genotype-phenotype similarities to some extent, but they also exhibit some differences with respect to the appearance and location of opacities within the lens." (PMID 17615540, 2007). "Variants in GJA3 have been associated with cataracts in humans, while mutations in GJB2 and GJB6, encoding for connexin-26 and 30, respectively, transmembrane proteins involved in the formation of gap junction in the cochlea, are known for their critical roles in hearing." (PMID 40025542, 2025). "Approximately 50% of cases may have a genetic cause, and GJA8 (encoding Cx50) and GJA3 (encoding Cx46) gene mutations account for about 20% of non-syndromic inherited cataract cases." (PMID 35457072, 2022). "In addition, in a rat model suffering from autosomal recessive congenital nuclear cataract, a missense mutation in gja3, p.Glu42Lys, has been reported." (PMID 29461512, 2018). "Thirty-two mutations identified in GJA3 are associated with human inherited cataracts." (PMID 28877251, 2017). "Almost all point mutations in Gja3 and Gja8 lead to variable dominant cataracts in mice and humans." (PMID 23300808, 2012). "Disruption of either Cx46 or Cx50, encoded by Gja3 or Gja8 genes, abolishes intercellular gap junction communication to impair fiber-to-fiber coupling, which disrupts lens current circulation and homeostasis, leading to different types of cataracts and/or smaller lenses." (PMID 34465795, 2021). "In a family of Tatar ethnicity with congenital autosomal dominant zonular cataracts, a deletion of 14 nucleotides was discovered in the GJA3 gene c.del1126_1139 (p.D376Qfs*69) in the heterozygous state in three cataract patients of two generations." (PMID 37367076, 2023). "For example, gja3/Cx46 has only been examined in the heart, yet, in our dataset, we find robust gja3/Cx46 expression in both heart and lens clusters, which suggests an enticing link to human GJA3/CX46, in which mutations are associated with cataracts." (PMID 35325106, 2022).
cataract (continued). "Congenital cataracts caused by GJA8 and GJA3 gene mutations show a variety of phenotypes, including nuclear, perinuclear, zonular, punctiform, pulverulent, jellyfish-like, star-shaped, full moon, Y-sutural, balloon-like, lamellar, and triangular phenotypes." (PMID 35457072, 2022). "Missense and frame-shift mutations of the genes encoding Cx46 and Cx50 (GJA3 and GJA8) have been identified in members of human families with inherited cataracts of various different phenotypes." (PMID 24575044, 2014). "In the present study, the Gja3 p.S405P mutation was detected in 4 SAMP strains (SAMP3, SAMP6, SAMP10, and SAMP11), among which only the SAMP3 strain is reported to develop cataract." (PMID 23586671, 2013). "Mutations of the genes that encode these connexins (GJA3 and GJA8) have been identified and linked to inheritance of cataracts in human families and mouse lines." (PMID 23596416, 2013). "Several genes have been associated with the presence of these two types of cataracts (CRYAA, CRYBA3/A1, CRYGC, CRYGD, CRYGS, connexin 46 [GJA3], and connexin 50 [GJA8])." (PMID 19390652, 2009). "Differences in the expression patterns of Cx46 and Cx50 may be the reason that GJA3 gene mutations cause cataracts only, while GJA8-related cataracts are accompanied with microcornea or glaucoma in half of the reported cases." (PMID 35457072, 2022). "As much as 70% of autosomal dominant cataract may be accounted for by missense coding mutations in the genes for crystallins, particularly CRYAA, CRYBB2, and CRYGD, and connexins (GJA3, GJA8)." (PMID 21042563, 2010). "Mutations in the corresponding genes MIP/Mip, GJA3/Gja3, and GJA8/Gja8 (encoding the gap junction membrane channel protein α3 and α8, respectively) have been shown to underlie some congenital, mainly dominant cataracts in mouse and man." (PMID 18483562, 2008). "In addition, sequencing of GJA3 and GJA8 genes in 41 congenital cataract probands revealed one known mutation in GJA3 gene inherited dominantly and two mutations in GJA8 gene (one novel and one known) segregating in an autosomal dominant fashion in cataract families." (PMID 29461512, 2018). "Disruption of either of the two connexin genes, connexin 46 (CX46, gap junction alpha 3 [GJA3]) and connexin 50 (CX50, GJA8), which are the major components of mammalian lens fiber cells, results in cataracts in mice." (PMID 23592915, 2013). "GJA3 and GJA8, but not GJA1, have been associated with cataracts in previous studies." (PMID 36009466, 2022).
congenital cataracts (19 papers, 2009 to 2023). "Studies have demonstrated that mutations in the GJA3 gene primarily lead to congenital cataracts, with varying phenotypes including nuclear and zonular powdered cataracts." (PMID 37367076, 2023). "Mutations of the genes encoding Cx46 or Cx50 (Gja3 or Gja8) are linked to the development of congenital cataracts in people." (PMID 36171977, 2022). "Predominantly heterozygous variants of GJA3, apart from one allele, are reported in individuals with congenital cataracts." (PMID 35008666, 2021). "In human, GJA3 (Cx43) has been associated with a variety of inherited forms of CC, though the most common remains zonular cataracts." (PMID 35008666, 2021). "A total of 88 high-risk pathogenic GJA3 nsSNPs were found, including 31 published nsSNPs associated with congenital cataracts and 57 novel nsSNPs predicted by all eight online tools." (PMID 32143568, 2020). "As the first report to relate the P187S mutation in GJA3, it expands the mutation spectrum of GJA3 in terms of congenital cataracts." (PMID 21647269, 2011). "As the first report to relate p.P187S mutation in GJA3, it expands the mutation spectrum of GJA3 in association with congenital cataracts." (PMID 21647269, 2011). "These include IHH involved in skeletal malformations, ROBO3 involved in horizontal gaze palsy with progressive scoliosis, PCSK9 involved in familial hypercholesterolemia, FAM83H related to amelogenesis imperfecta type 3 and GJA3 associated with congenital cataracts." (PMID 26861414, 2016). "Thus far, 16 mutations in GJA3 have been reported to be associated with congenital cataracts in humans." (PMID 21647269, 2011). "The crystallin (CRYAA, CRYAB, CRYGC, CRYGD, and CRYBA1) and connexin (GJA8, GJA3) genes were analyzed in 45 unrelated families from the Volga–Ural Region (VUR) with hereditary congenital cataracts." (PMID 37367076, 2023). "Increasing evidence over the last decade suggests that mutations in the Cx46 and Cx50 encoding genes, GJA3 and GJA8, respectively, are directly linked to human congenital cataracts in North and Central America, Europe and Asia." (PMID 24019978, 2013). "Among these, mutations in the GJA3 and GJA8 genes (that encode the lens gap junction proteins, CX46 and CX50) have been shown to underlie congenital cataracts, which most often exhibit dominant inheritance." (PMID 19756179, 2009). "The mutations of GJA3 (Cx46) and GJA8 (Cx50) are directly linked to human congenital cataracts." (PMID 22876138, 2012).
nuclear cataract (18 papers, 2007 to 2025). A cataract (disease) that involves the lens nucleus. "Variants in both GJA3 and GJA8 have been suggestively associated with age-related cataract, but only one variant in GJA3 had an ancestry-specific association with age-related nuclear cataract in Asians that approached genome-wide significance." (PMID 38927721, 2024). "The deletion of Gja3 results in recessive nuclear cataracts in mice, while a loss of Gja8 causes recessive phenotypes of small lenses and mild nuclear opacities." (PMID 23300808, 2012). "Deletion of the GJA3 gene (encoding Cx46) leads to severe nuclear cataracts in mice." (PMID 24019978, 2013). "We have genetically tested whether enhanced lens gap junction communication, provided by increased α3 connexin (Cx46) proteins expressed from α8(Kiα3) knock-in alleles in Gja8tm1(Gja3)Tww mice, could prevent nuclear cataracts caused by the γB-crystallin S11R mutation in CrygbS11R/S11R mice." (PMID 20844585, 2010). "In another ADCC family having 11 affected members in four generations (PC-12) with nuclear cataract, we have observed c.134G > C (p.Trp45Ser) in GJA3, a previously known substitution for ADCC." (PMID 36533234, 2022). "In another ADCC family with nuclear cataract, c.134G > C (p.Trp45Ser) in GJA3 has been detected." (PMID 36533234, 2022). "Both Gja8R205G/R205G Gja3+/+ and Gja8R205G/R205G Gja3−/− mice developed dense nuclear cataracts." (PMID 23300808, 2012). "Deletion of the GJA3 (Cx46) gene leads to severe nuclear cataracts in mice." (PMID 22876138, 2012).
breast carcinoma (12 papers, 2013 to 2024). "We disclosed the expression of five connexin isotypes by confirming the production of GJA1/Cx43, GJA3/Cx46 and GJB2/Cx26 and detecting, for the first time, GJA6/Cx30 and GJB1/Cx32 both in the human pre-menopausal mammary gland and breast carcinomas." (PMID 25383624, 2014). "The expression of GJA1/Cx43, GJA3/Cx46 and GJB2/Cx26 and, for the first time, GJA6/Cx30 and GJB1/Cx32 was revealed both in normal human mammary glands and breast carcinomas." (PMID 25383624, 2014). "Based on mRNA expression data, a comprehensive screening for five connexin isotypes, GJA1/Cx43, GJA3/Cx46, GJB2/Cx26, GJA6/Cx30 and GJB1/Cx32 was performed at the protein level in normal pre-menopausal breast glands and in a cohort of cancers representing all grades and major breast cancer subtypes." (PMID 25383624, 2014).
autosomal dominant congenital cataract (9 papers, 2010 to 2023). "Overall, we report four novel mutations in HSF4, CRYGA, CRYGC and PAX6, and one previously reported mutation in GJA3 that cause autosomal dominant congenital cataracts." (PMID 36670602, 2022). "In humans, GJA3 has been associated with a variety of inherited forms of cataract, the most common of which is nuclear or lamellar autosomal dominant congenital cataract, but also including autosomal recessive and age-related cataract." (PMID 36670602, 2022). "GJA3 encodes a 435 amino acid protein that has been identified as one of the disease-causing genes of autosomal dominant congenital cataract (ADCC), and at least 15 mutations of GJA3 have been reported to cause ADCC." (PMID 23592915, 2013). "Both connexin 46 (Cx46) and connexin 50 (Cx50), which are encoded by the GJA3 and GJA8 genes, respectively, have been reported to be associated with autosomal dominant congenital cataracts." (PMID 25517998, 2014). "At least 25 mutations have been reported in the literature to date in GJA3/Cx46 in families with autosomal dominant congenital cataracts." (PMID 23734083, 2013).
glaucoma (2 papers, 2018 to 2022). Increased pressure in the eyeball due to obstruction of the outflow of aqueous humor. "The severe secondary glaucoma phenotype in all the affected individuals could be one of the outcomes of the recessive mutation in GJA3 in this particular family." (PMID 29461512, 2018).
hearing loss (2 papers, 2010 to 2023). "The three most significantly associated SNPs for hearing loss are all located at the GJB2/GJB6 locus on 13q12.1, including rs870729 near GJB6 (p = 3.38×10−11, OR: 1.69), rs3751385 within GJB2 (p = 1.50×10−9, OR: 1.63), and rs7329467 within GJA3 (p = 6.87×10−8, OR: 1.68)." (PMID 20126254, 2010).
lung carcinoma (2 papers, 2019 to 2024). "However, for selected miRNAs, miR-610 was found to suppress lung cancer cell proliferation and invasion by targeting GJA3 expression, while exosomal miR-7977 has been identified as a novel biomarker for patients with lung adenocarcinoma and may function as a tumor suppressor in lung cancer." (PMID 39649094, 2024). "In addition, Connexin 46 (Cx46, GJA3) was found to be overexpressed in highly-invasive 95D than 95C lung cancer cells." (PMID 30642339, 2019).
melanoma (2 papers, 2019 to 2023). A malignant, usually aggressive tumor composed of atypical, neoplastic melanocytes. "In three melanoma cell lines, we also showed the loss of GJA1/Cx43 and the differential expression of GJB1/Cx32, GJB2/Cx26, GJA3/Cx46 and GJC3/Cx30.2." (PMID 30717194, 2019). "GJA3 (Cx46) mRNA levels were lower in MC (dCt = 11.75; SD = 0.66) than in melanoma cell lines A2058 (dCt = 9.85; SD = 0.25), WM983/A (dCt = 8.56; SD = 0.18) and HT199 (dCt = 6.99; SD = 0.22)." (PMID 30717194, 2019). "Cx46 (GJA3) immunoreactions showed diffuse cytoplasmic and occasionally cell membrane localization in primary melanocytes and in WM983/A and A2058 cell lines, and dominantly paranuclear staining in HT199 melanoma cells." (PMID 30717194, 2019).
age (1 paper, 2023). A temporal measurement of the time period elapsed since an identifiable point in the life cycle of an organism. "GJA3 has been implicated in age-related cataract development." (PMID 36975205, 2023).
cardiac conduction disorders (1 paper, 2021). "Loss of function of mammalian CX46 leads to cardiac conduction disorders, while the loss of gja3/cx46 in the zebrafish mutant dco causes defects in heart morphology and ventricular conduction pattern." (PMID 34557935, 2021).
deafness (1 paper, 2023). An inherited or acquired condition characterized by the complete loss of the ability to hear from one or both ears. "In terms of nearby genes—including the deafness- and cataract-associated connexins (GJA3, GJB2, and GJB6) —we found significantly reduced expression of only GJB6 (log2fc = −1.06, p = 3.47 × 10−4)." (PMID 37239394, 2023).
dysplasia (1 paper, 2009). A usually neoplastic transformation of the cell, associated with altered architectural tissue patterns. "Next to claudins, we observed up-regulation of gap junction proteins in dysplasia by 11 and 9-fold as well (Gja3, gap junction protein alpha-3 and Gjb4, gap junction protein beta-4)." (PMID 19529782, 2009).
Nystagmus (1 paper, 2013). Rhythmic, involuntary oscillations of one or both eyes related to abnormality in fixation, conjugate gaze, or vestibular mechanisms. "The proband with the Val28Val silent change in GJA3/Cx46 presented to us within the first year of life and was pseudophakic in the right eye and had a posterior subcapsular cataract in the left with nystagmus." (PMID 23734083, 2013).
persistent atrial fibrillation (1 paper, 2017). "This extended gene network contained a number of transcription factors (Tbx5, Hand2, Fhl2, and Gata4) and ion/calcium handling genes (Ank2, Cacna2d2, Scn5a, Kcnd2, Kcnj5, Myoz2, Casq2, Csrp3, and Gja3) of interest in the context of atrial fibrillation." (PMID 28720711, 2017).
degenerative diseases (1 paper, 2013). "In several SAMP strains, missense mutations were detected in the Prx, Ldb3, and Gja3 genes, which mutations have been found in various human degenerative diseases." (PMID 23586671, 2013).
GJA3 also shares sentences with these, for which no sentence is quoted: tumor (15 papers); cancer (13); Age-related cataract (7); glioblastoma (7); glioma (5); autosomal dominant cataract (4); breast tumor (3); microphthalmia (3); coralliform cataract (2); diabetes (2); genetic disorders (2); Age-related nuclear cataract (1); amelogenesis imperfecta type 3 (1); and Cortical Cataracts (1); bone cancer (1); Charcot-Marie-Tooth disease (1); erythrokeratodermia variabilis (1); familial hypercholesterolemia (1); hypopharyngeal cancer (1); Infertility (1); inflammatory bowel disease (1); inflammatory breast carcinoma (1); lung adenocarcinoma (1); lung adenoma (1); metastatic cancer (1); Microcornea (1); microdeletion syndromes (1); Obesity (1); osteosarcoma (1); pulmonary hypertension (1).
A further 1 disease shares a sentence with GJA3 in 1 paper.